RNU6-59P (RNA, U6 small nuclear 59, pseudogene)
Synonyms: RNU6-59
Gene: Small nuclear RNA gene on chromosome 13 (21,551,304 to 21,551,410, reverse strand). Ensembl gene ENSG00000207518.
Homologues: Orthologues: chimpanzee U6 (98% identical), macaque U6 (91% identical), pig U6 (77% identical). Paralogues in human: RNU6-393P (92% identical), RNU6-12P (91% identical), RNU6-13P (91% identical), RNU6-16P (91% identical), RNU6-32P (91% identical), RNU6-41P (91% identical), RNU6-1 (90% identical), RNU6-1181P (90% identical), RNU6-15P (90% identical), RNU6-17P (90% identical), RNU6-18P (90% identical), RNU6-2 (90% identical), and 1289 more.